DDX11L2 (DEAD/H-box helicase 11 like 2 (pseudogene) )
Synonyms: DDX11L17
Gene: Long non-coding RNA gene on chromosome 1 (180,931 to 184,937, forward strand). Ensembl gene ENSG00000308415.
Diseases named in the same sentence as DDX11L2 in open-access papers:
DDX11L2 is named in the same sentence as 1 disease in open-access papers, as found by Europe PMC text mining. Sharing a sentence is not in itself a finding about the gene and the disease.
DDX11L2 shares sentences with these, for which no sentence is quoted: lung adenocarcinoma (1 paper).